RN7SL520P (RNA, 7SL, cytoplasmic 520, pseudogene)
Gene: Miscellaneous RNA gene on chromosome 16 (75,698,531 to 75,698,816, reverse strand). Ensembl gene ENSG00000240199.
Homologues: Orthologues: chimpanzee Metazoa_SRP (99% identical), macaque Metazoa_SRP (91% identical). Paralogues in human: RN7SL1 (80% identical), RN7SL2 (80% identical), RN7SL597P (79% identical), RN7SL3 (78% identical), RN7SL220P (78% identical), RN7SL655P (78% identical), RN7SL126P (77% identical), RN7SL186P (77% identical), RN7SL258P (77% identical), RN7SL296P (77% identical), RN7SL386P (77% identical), RN7SL608P (77% identical), and 704 more.